LEP (leptin)
Diseases named in the same sentence as LEP in open-access papers (continued):
Sharing a sentence is not in itself a finding about the gene and the disease.
Obesity (continued). "Mice with pancreatic beta-cell-specific disruption of the STAT3 gene exhibited increased appetites, obesity, partial leptin resistance, and glucose intolerance." (PMID 29596388, 2018). "Despite the passing of more than two decades since the discovery of leptin, the cellular mediators (i.e., LepRb neurons) that mediate the largest component of the dramatic obesity phenotype of db/db mice remain undefined." (PMID 29914853, 2018). "Based on these facts, PTP1B is a highly plausible candidate for a leptin resistance factor and inhibiting its activity has emerged as a potential therapeutic strategy to treat obesity by restoring leptin sensitivity." (PMID 30383868, 2018). "Leptin, an adipokine that has a profound influence on the regulation of energy intake and that is consistently increased in obesity, has been shown to regulate the synthesis and secretion of FGF23, a major phosphaturic hormone." (PMID 30322116, 2018). "This study revealed that impaired leptin and insulin signaling mediated exacerbated obesity and glucose dysregulation through the interaction of the APP/PS1 genotype and HFD." (PMID 30096853, 2018). "During the development of obesity, plasma leptin levels are increased, while plasma adiponectin levels are decreased." (PMID 30463250, 2018). "Leptin is a hormone synthetized by adipocytes and serves as an indicator of energy storage; the increase in leptin was proposed to prevent obesity by decreasing feed intake." (PMID 30404613, 2018). "Leptin is acutely enhanced in infections and chronically enhanced during obesity, and neutrophils play an important role on the innate immune response." (PMID 29467755, 2018). "The obesity-related changes in hormone levels, in particular leptin, adiponectin, ghrelin, neuropeptide Y and agouti-related protein, are associated with reproductive dysfunction at both the hypothalamic-pituitary and the ovarian levels." (PMID 29743077, 2018). "In analogy with leptin, ghrelin stimulates hunger and food intake, promotes fat accumulation, and is related to obesity in patients with OSA." (PMID 30151379, 2018). "A trypsin inhibitor isolated from tamarind seed (TTI) has satietogenic effects in animals, increasing the cholecystokinin (CCK) in eutrophy and reducing leptin in obesity." (PMID 29322840, 2018). "Pregravid obesity is characterized by insulin and leptin resistance, high levels of circulating inflammatory markers IL-6 and CRP, in addition to chemokine IL-8 (p < 0.01)." (PMID 30131724, 2018). "It is well established that the anti-obesity hormone leptin regulates food intake and body weight via the hypothalamus." (PMID 29860205, 2018). "Understanding the relationship among Mel, leptin and energy metabolism is critical to improving strategies to limit obesity, especially in individuals exposed to environmental factors and circadian disturbances that affect Mel secretion." (PMID 29636725, 2018). "Although the central effects of leptin on hypothalamic and pituitary function have been examined extensively, the contribution of direct leptin actions on the ovary in obesity-related infertility/subfertility remains incompletely understood." (PMID 29728128, 2018). "Whereas leptin administration only has a negligible effect on the treatment of obesity, it has been demonstrated that its action can be improved by co-administration of leptin and one of its sensitizers." (PMID 30587816, 2018). "Protein tyrosine phosphatase 1B (PTP1B) negatively regulates leptin signaling by dephosphorylating JAK2, and the increased activity of PTP1B is implicated in the pathogenesis of obesity." (PMID 30383868, 2018). "Leptin, probably the key hormone in obesity, is produced by adipose tissue and controls both energy expenditure and food intake." (PMID 30463389, 2018). "Plasma concentrations of insulin and leptin increased markedly with HFD-induced obesity (chow ad libitum vs. HFD ad libitum)." (PMID 30210452, 2018).
Obesity (continued). "We next explored circulating leptin and oxytocin, and their relationship to the gut microbiota, due to their essential role in obesity and behavioral aspects related to this cohort." (PMID 29596446, 2018). "Several clinical studies have shown a correlation between increased plasma levels of both CRP and leptin in subjects with obesity, CVD, and diabetes." (PMID 29910808, 2018). "As reported in earlier studies, this appears to be related to obesity as indicated by a positive correlation between BMI and leptin and CRP." (PMID 29910808, 2018). "The expression of PTP1B and T cell PTP (TCPTP) upregulates in high-fat diet and obesity, and inhibits leptin-mediated STAT3 phosphorylation." (PMID 29868503, 2018). "We have proposed a mechanism for leptin’s adverse effects on male reproductive function, which will help to have a deeper insight into subfertility and infertility in the context of obesity and azoospermia." (PMID 29855380, 2018). "Mutations in human KSR2, MC4R, LEP and LEPR have been described as monogenic causes of obesity, confirming that this screen has relevance to human monogenic obesity disorders." (PMID 30563851, 2018). "Our study is the first study suggesting that exacerbated HFD-induced obesity and glycemic dysregulation in APP/PS1 transgenic mice are associated with impaired insulin and hypothalamic leptin signaling." (PMID 30096853, 2018). "This work can be summarized in 3 main concepts: the first is that leptin sensitivity can be modulated by this antidepressant in adulthood, even upon obesity." (PMID 29379096, 2018). "Imbalance of leptin/adiponectin (L/A) ratio was regarded as the biomarker of metabolism diseases, including obesity and diabetes." (PMID 30013512, 2018). "The hypothalamic pituitary adrenal axis, gonadal, growth hormone, leptin, sympathetic nervous system and adrenergic, dopaminergic, and serotoninergic central pathways, all seem interconnected and involved in obesity." (PMID 30108549, 2018). "Subjects with obesity exhibited significantly higher weight, BMI, waist circumference, insulin and leptin concentrations compared with age-matched and gender-matched normal weight individuals." (PMID 30266914, 2018). "In states of malnutrition or following fasting, circulating leptin levels are decreased, whereas in obesity, leptin levels are increased." (PMID 29868016, 2018). "Leptin is involved in hypothalamic control of satiety and weight regulation, and typically low CSF leptin levels are found in patients with obesity." (PMID 29985799, 2018). "In contrast, the risk factors for AP were different between men and women from the viewpoint of obesity and the adipose tissue-related biomarker, leptin." (PMID 30279628, 2018). "Obesity, common in DS, is known to induce chronic inflammation and apoptosis, with leptin and adiponectin key players in this process." (PMID 29587359, 2018). "In lieu of this variation, it can be concluded that leptin concentrations are affected by both SF and obesity, but their interaction is incompletely understood." (PMID 29479505, 2018). "The increased hypothalamic TCPTP in obesity probably occurs as a consequence of the heightened glucocorticoid and leptin levels that we have shown previously to drive TCPTP expression in the ARC." (PMID 30230471, 2018). "Leptin has a well-known role in the regulation of energy balance and is also considered to play a key role in the pathogenesis of obesity-related disorders." (PMID 29618984, 2018). "The mechanisms underlying the joint effect of obesity and DEHP on leptin level should be studied further." (PMID 29887939, 2018). "Plasma leptin was similar in lean p50−/− and WT and, as would be expected, was increased in obesity in both WT and p50−/− animals." (PMID 30251338, 2018). "We also evaluated the plasma levels of different obesity and T2D markers such as adiponectin, leptin, resistin, visfatin, PAI-1, and insulin." (PMID 30131766, 2018).
Obesity (continued). "Indeed, it would be interesting to investigate whether leptin signaling, via a microbial endocrinological-based mechanism, unites the separate observations that obesity is associated with leptin resistance as well as the risk of small intestinal bacterial overgrowth." (PMID 30761092, 2018). "In conclusion, we showed that IgG with micromolar affinity for leptin are naturally present in healthy subjects and in patients with obesity and T2D." (PMID 29795184, 2018). "Of note, we inactivated the Lepr hepatocyte-specific instead of a whole body knock out to prevent morbid obesity, which is seen in mice with completely disrupted leptin signaling." (PMID 30224299, 2018). "Our study is the first to characterize leptin-reactive IgG autoAbs in subjects with obesity and T2D." (PMID 29795184, 2018). "As previously reported, pregravid obesity resulted in increased plasma levels of metabolic hormones such as insulin, leptin, and lipocalin-2, indicative of insulin resistance, mild gestational hyperglycemia, and metabolic syndrome." (PMID 30131724, 2018). "There are data that blood plasma concentrations of leptin are 11.6 ng/ml in healthy subjects, and 34.7 ng/ml in patients with obesity." (PMID 30019195, 2018). "Our data offer a possible explanation for the role of leptin in tumor cell recruitment during obesity, when high levels of leptin production by white adipose tissue are observed." (PMID 29467755, 2018). "Although leptin resistance is documented in diet-induced obesity models as well as models of monogenic or polygenic obesity, the underlying mechanisms have not been fully determined." (PMID 29777232, 2018). "Yet, the same studies showed that total levels of leptin in the CSF are higher with obesity, indicating the existence of a central component in leptin resistance." (PMID 29748097, 2018). "These alterations allow us to map a metabolic link between restricted sleep duration and obesity via selected hormonal (leptin, cortisol, glucagon-like peptide 1 and ghrelin) functions and the metabolism of lipids and carbohydrates." (PMID 30463389, 2018). "In obesity, the excess of leptin is recognized for promoting an increase in the amount of immune cells in visceral adipose tissue." (PMID 29875681, 2018). "produced obesity characterized by increased body weight, % body fat, and plasma leptin levels as compared with the LF control group, as well as hepatic steatosis." (PMID 31061673, 2018). "It has been shown that leptin increases the inflammatory immune response, which suggests a pathway that contributes to the pathogenesis of obesity." (PMID 30618812, 2018). "This line of cellular evidence extends our understanding of molecular mechanism of leptin action on breathing, shedding light on the etiology of obesity-related hypoventilation or apnea." (PMID 29636698, 2018). "In this sense, our CAF-induced obesity rat model exhibited body weight/fat increase, hyperleptinemia and peripheral leptin resistance as indicated by the impairment of leptin-induced STAT3 phosphorylation in these tissues." (PMID 30441779, 2018). "The results from the present study indicate that obesity exerts important inflammatory effects on the homeostasis of intervertebral discs that are mediated via adipokines, mainly leptin and adiponectin." (PMID 29695079, 2018). "Ovalbumin-sensitized mice were established to prove the role of obesity on eosinophil regulation by leptin and OPN." (PMID 30473626, 2018). "Obesity-related low-grade inflammation originates from the adipose tissue, which enables the secretion of a variety of interleukins and adipokines such as leptin, adiponectin, and resistin." (PMID 30050954, 2018). "Currently, therapeutic strategies against obesity have been largely ineffective, such as 5-hydroxytryptamine modulators, β3 adrenoceptor agonists, lipase inhibitors, melanocortin 4 inhibitors, leptin agonists and ghrelin antagonists." (PMID 29619754, 2018).
Obesity (continued). "Differences in leptin or adiponectin corresponded to the degree of obesity in the models or indicated functional regulation of food intake (ghrelin)." (PMID 29587401, 2018). "Several studies demonstrated that leptin responsiveness decreases with obesity, aging and neurodegenerative diseases, a phenomenon called leptin resistance." (PMID 30692905, 2018). "Rodents which have the ability to develop obesity through genetic changes, such as leptin signaling defects (ob/ob mouse) or an autosomal recessive mutation in the fatty (fa) gene on chromosome 5 (Zucker-fa/fa–fatty rat) have mainly been used." (PMID 30103515, 2018). "For example, adipose tissue synthesize leptin and the circulating levels of leptin are strongly related to obesity." (PMID 30516928, 2018). "The multivariable logistic regression model adjusted for age, sex, obesity and tPa showed that higher leptin and lower adiponectin levels are independent predictors for PTS in this DVT patient cohort." (PMID 29720688, 2018). "Multivariable model of factors associated with ln leptin in men with SCI and based on sarcopenic-obesity status." (PMID 29949600, 2018). "In order to identify if there was a joint effect on leptin level when mice were jointly exposed to obesity and DEHP, we designed an experiment featuring 3 groups for 3 levels of DEHP exposure." (PMID 29887939, 2018). "In contrast to leptin, plasma levels of adiponectin are reduced in obesity, hypertension, hyperlipidemia, DM, and coronary atherosclerosis." (PMID 30071056, 2018). "Blocking or inhibiting inflammation in the hypothalamus prevents leptin and insulin insensitivity and obesity induced by a HFD." (PMID 30519364, 2018). "Targeting molecules required for the development of leptin resistance is a potentially effective therapeutic approach for preventing the obesity epidemic." (PMID 30383868, 2018). "Studies in psoriasis patients have also found higher levels of leptin, an adipokine that is positively correlated to obesity." (PMID 29680995, 2018). "The leptin-notch signaling axis targeting has been projected as potential mediator for benefitting PC patients with obesity." (PMID 30567565, 2018). "Previous studies reported that in obesity, the ability of leptin to cross the blood–brain barrier is reduced." (PMID 29593493, 2018). "Under lean conditions leptin acts as an anti-obesity hormone, signaling through activation of leptin receptors at the hypothalamus to reduce feeding behavior." (PMID 30405455, 2018). "The most common of the single gene alterations affect the leptin gene (LEP), resulting in congenital leptin deficiency that manifests as intense hyperphagia, EOO and severe obesity associated with hormonal and metabolic alterations." (PMID 29217499, 2018). "There are several plausible mechanisms relating altitude and obesity,including hypoxia, mean annual temperature, physical activity, leptin signaling,metabolic demands, and ethnicity." (PMID 28853330, 2018). "Lastly, increased circulating levels of leptin in obesity lead to hypothalamic leptin resistance, turning down anorexigenic and energy expenditure signals and further contributing to aggravate obesity." (PMID 30692905, 2018). "The hypothalamic inflammatory process that occurs in obesity impairs insulin and leptin signaling in this tissue and, consequently, can decrease WAT browning." (PMID 29643769, 2018). "mTOR is regulated by leptin which, like in obesity, is upregulated in diabetes due to higher levels of fat and blood glucose." (PMID 30618559, 2018). "The UCD-T2DM and ZDSD rats essentially represent polygenic late-onset obesity with insulin resistance and eventual beta cell insufficiency, while possessing normal leptin signaling." (PMID 29463026, 2018). "Obese subjects usually have high levels of circulating leptin, which is considered a proinflammatory adipokine contributing to the low-grade chronic inflammation in obesity." (PMID 29675134, 2018).
Obesity (continued). "Obesity-induced ROS can affect adipocytes to secrete more leptin, which together with insulin, negatively regulate T3-release and thereby inhibit testicular functions." (PMID 30205828, 2018). "With many functional relationships regulating the orexigenic-anorexigenic signal balance, it is not surprising that variation in the genes involved in the melanocortin-leptin pathway can give rise to severe obesity." (PMID 30121879, 2018). "Following this catch up period, adult 129S2/Sv Nnat null mice had decreased energy expenditure, blunted leptin sensitivity and hyperphagia, and were more susceptible to both aging and HFD-induced obesity in later-life." (PMID 30279096, 2018). "Although serum ghrelin and leptin levels were found to be normal in women with PCOS; yet, there is a relationship, possibly linked to obesity, hyperinsulinemia and insulin resistance between these levels and metabolic profile of Saudi PCOS." (PMID 30131073, 2018). "Leptin, an adipokine of the obesity (ob) gene, has been shown to regulate food intake and energy expenditure via a hypothalamic-mediated effect." (PMID 30473626, 2018). "In established obesity, omentectomy eliminates the omental production of inhibitors of the leptin and insulin effects, particularly CRP and IL-6." (PMID 29367725, 2018). "We do know that obesity and exercise both influence the balance of pro-inflammatory and anti-inflammatory cytokines including leptin, and that distinct leptin receptor isoforms have been described in human skeletal muscle and adipose tissue." (PMID 29949600, 2018). "Although more detailed evidence is needed, AR is assumed to exhibit an anti-obesity effect by enhancing leptin signaling, which has been shown to activate sympathetic nerves." (PMID 29895265, 2018). "This supports the possibility of treating obesity via the leptin pathway, which can also be applied to treatment of chronic liver disease." (PMID 30424542, 2018). "Examining pulmonary effects is complicated, as it can be difficult to distinguish the role of leptin from the effects of obesity, as well as the biology of adipose tissue." (PMID 29975721, 2018). "This inflammation in turn contributes to both insulin and leptin resistance, promoting further obesity and subsequently diabetes." (PMID 29743077, 2018). "In humans, limited evidence has reinforced the relationship between leptin and ventilatory function in obesity." (PMID 29975721, 2018). "Strikingly, the ARC becomes selectively leptin resistant in mice with diet-induced obesity, whereas other hypothalamic and extrahypothalamic nuclei remain leptin responsive." (PMID 29632515, 2018). "Genetically obese (leptin-deficient ob/ob) mice also showed much higher lipogenic activities in WAT than did the wild-type mice, indicating that obesity induces ectopic lipogenesis, in addition to fat accumulation." (PMID 30082908, 2018). "The resulting adipose tissue remodeling, including the white-to-brown phenotypic switch and the suppression of leptin, results in an anti-obesity and anticancer phenotype." (PMID 30036185, 2018). "In contrast to these data, a prevailing model proposes that impaired leptin transport across the BBB triggers the development of leptin resistance in obesity." (PMID 29748097, 2018). "Obesity is characterized by an increase in circulating leptin and a decrease in leptin receptor expression, leading to leptin resistance and disrupted leptin signaling." (PMID 30405455, 2018). "Obesity-stratified logistic regression analysis confirmed that lower adiponectin (OR, 0.49; 95% CI, 0.38–0.64) and higher leptin (OR, 1.41; 95% Cl, 1.25–1.58) levels predicted PTS." (PMID 29720688, 2018). "Taken together, our data reveal that leptin-reactive IgG are present in healthy subjects, obese, and diabetic patients but display altered affinity kinetics in obesity." (PMID 29795184, 2018).